CDH2 (cadherin 2)
Diseases named in the same sentence as CDH2 in open-access papers (continued):
Sharing a sentence is not in itself a finding about the gene and the disease.
glioma (188 papers, 1995 to 2026). A benign or malignant brain and spinal cord tumor that arises from glial cells (astrocytes, oligodendrocytes, ependymal cells). "The association of phGBM progression with cadherin-E (CDH1) and CDH2 is mainly unexplored, whereas the literature on the association of CDH1 and CDH2 expression with adult glioma progression is controversial." (PMID 35216113, 2022). "The EMT process in gliomas may be exacerbated by enhanced CDH2 expression, which is associated with unfavorable prognostic outcomes." (PMID 41012498, 2025). "A growing body of evidence suggests that CDH2 is closely associated with glioma." (PMID 34796102, 2021). "q-PCR was conducted to prove that mRNA expression of Spp1 and CDH2/N-cadherin are down-regulated by probiotic combination in glioma mice (Spp1, p < 0.05; N-cadherin, p < 0.05)." (PMID 36147842, 2022). "Our results demonstrated that deletion of the SPAG5 gene reduced the expression of CDH2 and inhibited the proliferation of glioma cells, whereas restoration of CDH2 restored the proliferation of glioma cells." (PMID 34796102, 2021). "The biological role of cadherin 2 (CDH2) was also mostly reported in glioma with prognostic significance (Chen, Cai & Jiang, 2018)." (PMID 32714651, 2020). "Camand and collaborators explained this contradiction with a difference between Cdh2 mRNA and protein expression level, with the former highly expressed and the latter scarcely expressed in glioma samples." (PMID 31426573, 2019). "We previously demonstrated that Cdh4 can compete with Cdh2 for membrane localization in mouse glioma cells, inducing a cadherin switch similar to that described in the EMT process occurring during epithelial tumor progression." (PMID 31426573, 2019). "Only GBM23, the glioma culture with the lowest Cdh4 expression level, shows Cdh2 protein localization in the cell-cell junction region forming septa between adjacent cells." (PMID 31426573, 2019). "The same authors further demonstrated that Cdh2 downregulation increases cell migration of both normal neural cells and glioma cells showing an anti-migratory role for Cdh2 in neural tissue." (PMID 31426573, 2019). "It has also been demonstrated that both CDH2 and N-cadherin down-regulations dramatically change glioma cells migratory behavior and increases invasiveness of this non-epithelial tumor." (PMID 25008066, 2014). "The analysis of RNA-seq data from TCGA databases showed significant upregulation of genes encoding mesenchymal markers and EMT regulators such as CDH2 (coding N-cadherin), VIM (coding Vimentin), SNAIs and TWISTs in tumor samples, particularly in high-grade human gliomas (grade 4) and MES-GBMs." (PMID 36900355, 2023). "Glioma invasion may be compromised by a reduction in Cdh2 expression in vivo, an important molecule for tumor cell–endothelial cell adhesion." (PMID 35328529, 2022). "Our data suggest that SPAG5 is an oncogene that promotes glioma by downregulating CDH2." (PMID 34796102, 2021). "It has also been shown that CDH2 could act as a potential prognostic and predictive biomarker for the grading and treatment of gliomas." (PMID 34530820, 2021). "Furthermore, glioma patients with low CDH2 expression had an improved prognosis and benefited from temozolomide therapy." (PMID 34530820, 2021). "Other studies also indicated CDH2 may be functionally correlated with tumorigenesis in glioma cells and involved in mediating glioma cell migration." (PMID 25866482, 2015). "RelB knockdown cells displayed diminished RNA expression of the mesenchymal genes N-Cadherin/CDH2, SMAD2 and TGFβ3, as well as lower levels of YKL-40/CHI3L1, a biomarker of aggressive and recurrent gliomas that is very strongly associated with the mesenchymal glioma subtype." (PMID 23451236, 2013). "By studying TCGA, Chinese Glioma Genome Atlas (CGGA), and Rembrandt databases, CDH2 expression was identified as significantly higher in grade 4 than in grades 2 (P < 0.001) or 3 (P < 0.001)." (PMID 40679044, 2025).
glioma (continued). "It has been observed that FOXD2-AS1 long non-coding RNA (lncRNA) induced glioma cell proliferation and EMT by CDH1, CDH2, and VIM regulations through miR-506-5p sponging." (PMID 37051101, 2023). "In our study, we found that the expression of VCAM1, ICAM1, CDH2 was down-regulated, while the expression of SDC2 was up-regulated after knocking down the expression of GNG5 in glioma cells." (PMID 34098960, 2021). "This suggests that in glioma cells, the SPAG5 gene regulates tumor cell proliferation through the CDH2 signaling pathway." (PMID 34796102, 2021). "CDH2 encodes the N-cadherin protein, and the previous study has confirmed that the expression of CDH2 in patients with high-grade glioma is higher than that in patients with LGG, and patients with high expression of CDH2 show poor prognosis." (PMID 34796102, 2021). "The risk score was positively correlated to the oncogenes S100A4, TWIST1, CDH2, and POSTN, which were critically involved in glioma migration and invasion." (PMID 32733879, 2020). "In keeping with our previous analysis, we noted that Cluster A, which is composed mainly of H3WT glioma cells, strongly resembles post-EMT cells and most highly expresses canonical post-EMT markers including CDH2, CDH6, and VIM." (PMID 33319914, 2020). "Of the genes identified in the bulk RNA-seq analysis, only FN1, CDH2, and CDH11 were expressed in the glioma single-cell RNA-seq data, so we also visualized VIM as a post-EMT marker and SFRP1 as a pre-EMT marker." (PMID 33319914, 2020). "CDH2 was expressed in the majority of glioma cases, with no expression found in 10.3% of high-grade GBM." (PMID 41012498, 2025). "Our results revealed that SPAG5 knockdown could reduce CDH2 expression, and overexpression of CDH2 could antagonize the effects of SPAG5 knockdown in glioma cells." (PMID 34796102, 2021). "We found that decreasing the expression level of GNG5 in glioma cells could significantly affect the expression of VCAM1, ICAM1, CDH2, and SDC2, which are key molecules of cell adhesion molecules." (PMID 34098960, 2021). "The prognostic analysis shows that high CDH2 expression is closely related to poor glioma prognoses and that there is no subsequent benefit obtained from temozolomide treatment." (PMID 34880371, 2021). "Overexpression of CDH2 with SPAG5 depletion could restore the proliferation and inhibit the apoptosis of glioma cells, which also promoted cell migration and invasion." (PMID 34796102, 2021). "The quantitative real-time PCR method was used to evaluate mRNA expression of SEMA3(A-G), neuropilins (NRP1 and NRP2), plexins (PLXNA2 and PLXND1), cadherins (CDH1 and CDH2), integrins (ITGB1, ITGB3, ITGA5, and ITGAV), VEGFA and KDR genes in 59 II-IV grade glioma tissues." (PMID 33036421, 2020).
prostate carcinoma (167 papers, 2011 to 2026). A carcinoma that arises from epithelial cells of the prostate gland. "CDH2 rs643555 was significantly associated with prostate cancer prognosis in both stages and remained significant after controlling for known risk factors." (PMID 30993852, 2019). "CDH2 rs643555 may be a promising biomarker to identify patients at high risk of poor prostate cancer prognosis." (PMID 30993852, 2019). "However, the association between CDH2 rs643555 and prostate cancer progression was replicated across both sets of the study, which would reduce false‐positive findings." (PMID 30993852, 2019). "In summary, in this study we bring evidence that N-cadherin upregulation in prostate cancer cells appears to result from the binding of AR variants to AREs in intron 1 of the CDH2 gene followed by histone H4 acetylation, but also from a decrease of endogenous AR-FL." (PMID 29069764, 2017). "Our findings of CDH1 and CDH3 promoter hypermethylation in NSCLC tumors, with relatively stable methylation for CDH2, are consistent with studies in gastric and prostate cancers." (PMID 40860670, 2025). "Past studies have shown that patients with prostate cancer who had lymph node metastases or high-grade primary tumors generally expressed more CDH2 than patients with low-grade tumors." (PMID 40693059, 2025). "The transcription factor TWIST similarly represses CDH1 expression and upregulates CDH2 in prostate cancer cell lines." (PMID 34831167, 2021). "We further investigated the prognostic effects of CDH2 expression on BCR‐free survival after RP for prostate cancer." (PMID 30993852, 2019). "The expression of CDH1 (E-cadherin) was suppressed, while CDH2 (N-cadherin) was highly expressed in metastatic prostate cancer tissues." (PMID 30631151, 2019). "In prostate cancer patients, CDH2 mRNA only modestly correlated with N-cadherin protein." (PMID 36880595, 2023). "CDH2 could mediate calcium-dependent cell adhesion and promote prostate cancer cells metastatic activity, and its aberrant expression has been reported in both metastatic cancer and CRPC." (PMID 31620371, 2019). "In addition, functional studies support the prognostic value of CDH2 in prostate cancer." (PMID 30993852, 2019). "The results showed that the expression levels of CDH2, SNAI1, ZEB1, and ZEB2 were significantly downregulated in prostate cancer compared to controls, while the expression of CDH1 was significantly upregulated." (PMID 40693059, 2025). "By using luciferase reporter assay we validated that CDH2 and Golm-1 are miR-145-5p target genes also in the Thymic Carcinoma cell lines TC1889, as already published, respectively, for gastric and prostate cancer." (PMID 28486946, 2017). "Furthermore, the KM plotter and GEPIA results demonstrated that when prostate cancer progresses, there are changes in the expression of CDH1, CDH2, VIM, SNAI1, ZEB1, and ZEB2." (PMID 40693059, 2025). "Moreover, lncRNA activated in prostate cancer progression (lncAPP) accelerated prostate cancer progression by competitively sponging miR-218 to enhance ZEB2 and CDH2 expression." (PMID 32351538, 2020). "We found three groups of genes in the EMT differentially expressed list: a) known EMT genes (e.g. CDH1, ZEB1, TGFB, CDH2, VIM, TIMP1), b) EMT genes previously unknown in prostate cancer (LSR, S100A14, DPYSL3) and c) novel EMT genes (including C1orf116)." (PMID 28651527, 2017). "SSX2 knockdown, in the 22Rv1 prostate cancer line, demonstrated a large fold change in many different EMT associated genes (TWIST1, ZEB2, MMP2, VIM, CDH1, CDH2) however these genes did not respond in an anticipated or canonical way." (PMID 27276714, 2016). "Analysis of progression-free survival of prostate cancer patients (TCGA) indicated that neither ARF3 nor CDH2 mRNA levels could stratify patient groups with altered survival." (PMID 36880595, 2023).
prostate carcinoma (continued). "For example, in induced pluripotent stem cells (iPSC) and prostate cancer cells, mesenchymal genes, such as ZEB1, ZEB2, CDH2, TWIST and SNAI1/2, are enriched with EZH2 binding, but not epithelial genes such as CDH1 or SNAI3." (PMID 37175580, 2023).
gastric cancer (141 papers, 2013 to 2026). A primary or metastatic malignant neoplasm involving the stomach. "By analyzing gastric cancer (GC) patients in two independent cohorts, Luo and co-workers showed that cadherins CDH2, CDH6, CDH7 and CDH10 were significantly associated with a poor GC prognosis." (PMID 35631574, 2022). "Beyond its established role as a canonical marker of EMT, aberrant CDH2 expression has been implicated in the aggressive progression of various malignancies, including lung, liver, and gastric cancers, primarily by enhancing cellular migratory and invasive capacities." (PMID 41596365, 2026). "We previously showed that the intestinal-type with epithelial characteristics and the diffuse-type with mesenchymal characteristics can be clearly distinguished using the ratio of CDH1 (E-cadherin) mRNA and CDH2 (N-cadherin) mRNA in gastric cancer." (PMID 26625258, 2015). "miR-145 attenuates gastric cancer cell migratory and invasive abilities in vitro by targeting N-cadherin (CDH2)." (PMID 26146543, 2015). "For example, the expression of CDH2 in gastric cancer cells was up-regulated following demethylation." (PMID 24705471, 2014). "CDH2 is upregulated in various cancers, including colorectal, bladder, lung and gastric cancers." (PMID 33329729, 2020). "In gastric cancer, a high TWIST protein expression level was associated with a reduction in CDH1 protein and with the increased CDH2 which may enhance cell motility in several cancer types." (PMID 27842518, 2016). "The results of this study showed that TGFβ1, TGFβ2 and TGFβ3 were positively correlated with EMT, CDH2, VIM and ZEB1 and significantly negatively correlated with CDH1 in multiple gastric cancer datasets." (PMID 36119489, 2022). "In multiple gastric cancer datasets, TGFβ were positively correlated with EMT score and mesenchymal markers (CDH2, VIM and ZEB1), while significantly negatively correlated with epithelial marker CDH1." (PMID 36119489, 2022). "It has been reported previously that CTNND1, EZH2, BCL2L2, CDH2, VIM, and EGFR have positive correlation to proliferation, invasion, and poor prognosis of gastric cancer." (PMID 28694563, 2017). "We found a decreased expression of the epithelial markers CDH1, EpCAM, and increased expression of the mesenchymal markers CDH2, Vimentin, ZEB1, Snail, MMP14 and Twist in un-captured cells in gastric cancer cell lines AGS, SGC7901 and BGC-823." (PMID 27654478, 2016). "In contrast, CDH2 was downregulated in gastric cancer, while EPB41L3, DNASE2, and XPC showed no significant expression differences between gastric cancer and normal tissues." (PMID 40393971, 2025). "We continued the qRT-PCR analysis of the samples, and among the EMT-related markers, the expression levels of mesenchymal markers CDH2 and ZEB1 genes were significantly reduced in gastric cancer cells after TGFβ gene silencing, while CDH1 expression was not significantly altered." (PMID 36119489, 2022). "Similarly, in gastric carcinoma, dual targeting of CDH1 and CDH2 suppressed migration and invasion." (PMID 40860670, 2025). "Finally, we found that the imbalance of 11 immune regulatory factors could predict the overall survival time of gastric cancer, including EZH2, NRP1, CD59, OsBPL1aBCL11B, BASP1, HNMT, CXCR4, ASGR2, ANXA5, CDH2." (PMID 34322132, 2021).
ovarian carcinoma (132 papers, 2007 to 2026). A malignant neoplasm originating from the surface ovarian epithelium. "Consistent with this phenotype, genes involved in cell adhesion, such as cdh2 and cd44a, which have been implicated in ovarian cancer, were upregulated at the mRNA level in eif4e1b mutant gonads (F and Dataset EV7)." (PMID 38177902, 2024). "The diagnostic value of CDH2 expression in ovarian cancer was subsequently assessed." (PMID 41596365, 2026). "To further characterize changes in CDH2 expression during chemotherapy in ovarian cancer, we cross-validated our findings using Single-cell RNA sequencing (scRNA-seq) data from clinical ovarian cancer samples (GSE211956)." (PMID 41596365, 2026). "In conclusion, this study identifies CDH2 as a clinically significant hub gene that converges with cisplatin resistance and poor prognosis in ovarian cancer." (PMID 41596365, 2026). "The heatmap revealed that PIWIL1, DNMT3B, OCT4, NANOG, and CDH2 were increased in most ovarian cancer samples, while CDH1 was downregulated, thus delineating clear expression differences between cancer and control samples." (PMID 41596471, 2026). "Simultaneously, to understand the biology behind the key signatures, the protein expression of ALKBH5, WTAP, ELAVL1, and CDH2 in ovarian cancer was analyzed using CPTAC datasets." (PMID 37684273, 2023). "CXCR7 overexpression not only significantly enhances histone modification and transcription, but also indirectly induces the expression of mesenchymal markers such as SNAI1, SNAI2, and CDH2 to promote migration and invasion of ovarian cancer cells." (PMID 33829065, 2021). "This work provides a foundation for future studies to evaluate whether CDH2 serves as a functional biomarker or a targetable therapeutic vulnerability in refractory ovarian cancer." (PMID 41596365, 2026). "The results showed that the gene and protein expression patterns of ALKBH5, ELAVL1, and CDH2 were increased in ovarian cancer, while the protein expression of WTAP did not match the gene expression, suggesting gene transcription and translation may be involved in its preservation." (PMID 37684273, 2023). "OC-MQs increased mesenchymal markers’ expression, including SNAI1, CDH2, FN, VIM, and ZEB1, in ovarian cancer cells." (PMID 39937005, 2025). "Functionally, TGFBI affected the migration and invasion of ovarian cancer cells by regulation of epithelial mesenchymal transition (EMT) markers (CDH1 and CDH2) and extracellular matrix (ECM) degradation proteins (MMP-2)." (PMID 38395907, 2024). "CDH2, ALKBH5, ELAVL1, and WTAP are the key regulators that exert a critical impact on the development and prognosis of ovarian cancer." (PMID 37684273, 2023). "Next, utilizing the ssGSEA algorithm and conducting overall survival analyses, we have identified the key prognosis-related immunological signatures in ovarian cancer to be ALKBH5, WTAP, ELAVL1, and CDH2 as the regulators." (PMID 37684273, 2023). "Subsequently, we used the ssGSEA algorithm and overall survival analyses to identify the key prognosis-related immunological signatures in ovarian cancer, which included WTAP, ELAVL1, CDH2, and ALKBH5." (PMID 37684273, 2023). "In ovarian cancer cells, overexpressing of HK2 enhanced cell motility by inducing of EMT-related proteins, such as CDH2, fibronectin, MMP9, ZEB1, ZEB2 and vimentin." (PMID 35953860, 2022). "Similarly, we observed that silencing TGFBI in SKOV-3 and Caov-3 cells resulted in increased expression of CDH1 (E-cadherin) and decreased CDH2 (N-cadherin), suggesting that TGFBI affected the metastatic capabilities of ovarian cancer cells via EMT reprogram." (PMID 38395907, 2024). "In addition, PF treatment exerts powerful anti-cancer effects via the upregulation of CDH2, the downregulation of CDH1, and the inhibition of the NF-kB signaling pathway in ovarian cancer cells and cisplatin-resistant ovarian cancer cells." (PMID 38140352, 2023).
ovarian carcinoma (continued). "Additionally, significant correlations were observed between the methylation of ALKBH5, WTAP, ELAVL1, CDH2 and immunoinhibitors, immunostimulators, and MHC molecules in ovarian cancer using Spearman’s correlation analysis." (PMID 37684273, 2023). "Four ovarian cancer cell lines (PEO1, OVCA429, SKOV3, and HEYA8) representing the E, Intermediate E (IE), Intermediate M (IM), and M states along the EMT spectrum were examined at the two classical E and M genes of the cadherin family – E-Cadherin (CDH1) and N-Cadherin (CDH2)." (PMID 35637517, 2022). "Chao and his colleagues reported that LMX1A could inhibit the EMT pathway by upregulating the epithelial marker CDH1 and downregulating the mesenchymal markers CDH2 and FN1 by repressing the EMT-related transcription factors SNAIL, SLUG, and SIP1 in ovarian cancer." (PMID 32751497, 2020). "In the ovarian cancer tissues, further significant positive correlations were observed between DAB2 and CSC markers (CD34, ALDH1A1, CD117 (Kit)) and mesenchymal markers (MMP9, SNAI1 and MMP3) and negative correlations with mesenchymal markers (CDH2, FOXC2 and SOX10)." (PMID 37815603, 2023).